XIAP (X-linked inhibitor of apoptosis)
Diseases named in the same sentence as XIAP in open-access papers (continued):
Sharing a sentence is not in itself a finding about the gene and the disease.
cancer (continued). "It is reasonable to hypothesize that based on mechanistic studies to the role of XIAP in cancer and non-malignant conditions increased tumor XIAP level trigger the recruitment of myeloid derived cells to the tumor which modulates the anti-tumor immune response." (PMID 36472768, 2023). "However, whether XIAP expression can serve as an important prognostic and/or predictive marker is not conclusive for all cancers." (PMID 34199946, 2021). "Therefore, renal protection during cisplatin therapy would require targeted upregulation of XIAP and pAkt in renal tubular cells and not in nonkidney cancer cells for before such an approach could be applied in a clinical setting." (PMID 32832155, 2020). "The XIAP mRNA and protein reciprocally regulate MDM2 protein stability through different mechanism, which is likely a homeostasis for MDM2 expression, suggesting that the interaction of the two factors and their deregulation may play a critical role in cancer pathogenesis." (PMID 25888903, 2015). "Moreover, inhibition of BCL2 and XIAP might not induce direct antiproliferative effects in cancer cells but rather a sensitisation to exogenous apoptosis stimuli similar to chemotherapy or radiation." (PMID 22797576, 2012). "The results of anti-cancer activity experiments showed that 1-(4-methylpent-2-enyl)-2-(4- phenylbut-2-enyl)disulfane could significantly inhibit the proliferation, induce the apoptosis of CNE2 cells in a dose dependent manner, and could significantly enhance the activity of XIAP." (PMID 20714320, 2010). "On the other hand, in HMGB1-stimulated HCT116 cancer cells, C6 was revealed to suppress the activation of ERK1/2, CDK1, and AKT and the down-regulation of anti-apoptotic XIAP but not c-IAP1, c-IAP2, and Bcl-xL and up-regulate pro-apoptotic Bax and caspase-3/7." (PMID 35408786, 2022). "Owing to the notion that XIAP and MDM2 typically undergo amplification and/or overexpression in most forms of cancer, these non-transformed, non-tumorigenic cell lines were chosen for their physiological expression of target genes." (PMID 28542129, 2017). "In contrast, the expression of anti-apoptotic protein XIAP and transcription factor Sp1, which has shown to be suppressed by ISO in human cancer cells, was not affected upon ISO treatment in Cl41 cells." (PMID 24797581, 2014). "The effectiveness of cancer therapy was the highest when several IAPs were downregulated simultaneously, suggesting that multiple IAPs rather than an individual IAP (e.g., XIAP) should be targeted." (PMID 27335822, 2013). "In this case, SMAC-mimetics do not trigger apoptosis by displacing caspases from XIAP, but by inducing TNF and rendering cancer cells sensitive to autocrine TNFα." (PMID 20461078, 2010). "Here, we screened a preclinical/clinical compound library consisting of 3471 bioactive compounds and identified embelin, a potent nonpeptide cell‐permeable inhibitor of XIAP, specifically targeting SHP2, establishing a connection between these two cancer‐related proteins for the first time." (PMID 39992860, 2025). "Unlike the overexpression of XIAP in most human cancer tissues, XAF1 is ubiquitously expressed in normal and fetal tissues but weakly expressed or even undetectable in most human cancer cell lines and human cancer tissues including gastric, colon and pancreatic cancer." (PMID 24980821, 2014).
tumor (433 papers, 2004 to 2026). "It has been shown that a high expression of XIAP is associated with poor prognosis and drug resistance in a variety of tumor types." (PMID 39917292, 2025). "A new cIAP1/2 and XIAP antagonist called ASTX660 makes HNSCC tumour cells more susceptible to TNF‐, TRAIL‐ and FasL‐induced cell death." (PMID 38044583, 2024). "IL-6-activated STAT3 in turn promotes tumor cell survival by inducing the expression of Bcl-2, survivin, and X-linked inhibitor of apoptosis protein (XIAP), the overexpression of which is related to increased chemoresistance." (PMID 38520006, 2024). "X-linked apoptosis inhibitor (XIAP), one of the best-evaluated candidates, has been associated with advanced tumor stage and poor histopathological grading as well as shortened survival in previous works." (PMID 38410284, 2024). "The protein known as the X-linked inhibitor of apoptosis (XIAP)-associated factor 1 (XAF1) is a tumor-suppressor gene expressed in many types of tumor cells, including lung adenocarcinoma and colon tumor cells." (PMID 37569299, 2023). "In human tissues, X-linked inhibitor of apoptosis protein (XIAP) is a powerful suppressor of apoptosis, which has recently been confirmed to be a tumor suppressor." (PMID 37854681, 2023). "Another SMAC mimetic, called AZ58, led to a reduction of cIAP1, cIAP2 and XIAP expression, sensitized different BC cell lines to gemcitabine and cisplatin, and caused inhibition of tumor growth in a UMUC-6 mouse xenograft model." (PMID 36845731, 2023). "Both Bcl-2 apoptosis regulator (Bcl-2) and X-linked inhibitor of apoptosis protein (XIAP) were recognized as anti-apoptosis factors that contribute to tumor progression, while Bcl-2-associated X (BAX) and caspase-3 were known as apoptosis markers." (PMID 35008959, 2022). "XIAP overexpression in tumor cells has been linked to tumor aggressiveness and has been described as a mediator of resistance to chemotherapy and targeted therapy in various malignancies." (PMID 35865469, 2022). "X-linked inhibitor of apoptosis (XIAP)-associated factor 1 (XAF1) is a pro-apoptotic tumor suppressor that is originally found to antagonize the anti-caspase activity of XIAP." (PMID 35902580, 2022). "Patients with higher tumor levels of XIAP showed an increased risk of relapse, as observed in database analysis." (PMID 35406442, 2022). "The combination caused a significant reduction in the tumor volumes by the down-regulation of several proteins such as survivin or XIAP (X-linked inhibitor of apoptosis protein)." (PMID 35011730, 2022). "Many studies have demonstrated that antisense oligonucleotides or small interfering RNA (siRNA) can suppress tumor cell proliferation, cause apoptosis, and make tumor cells more sensitive to chemotherapeutic treatments by inhibiting XIAP expression." (PMID 36430771, 2022). "Tumor size, extranodal extension, triple-negative status and poorly differentiated subtypes showed direct associations with XIAP expression in the Middle Eastern population." (PMID 35406442, 2022). "According to this literature review, the mechanisms used by sestrin 2 to inhibit tumor growth are mainly associated with mTOR, iNOS, XIAP, and HIF-1α signaling pathways." (PMID 34784907, 2021). "We also report in a uni- and multivariate analysis of more than 1200 patients that higher XIAP tumor expression was associated with lower pCR rate to anthracycline-based neoadjuvant chemotherapy." (PMID 34199946, 2021). "XIAP, the most potent inhibitor of cell death pathways, is linked to chemotherapy resistance and tumor aggressiveness." (PMID 34199946, 2021). "Second, it is also possible that while high expression of XIAP is associated with better survival in ccRCC, XIAP can still be a target for tumor elimination." (PMID 34384473, 2021).
tumor (continued). "The anti-apoptotic proteins (Bcl-xL and X-linked inhibitor of apoptosis (XIAP)) are also degraded in autophagy, consequently endorsing the elimination of tumor cells by NK cells and cytotoxic lymphocytes via the granzyme pathway." (PMID 33525678, 2021). "The X-linked inhibitor of apoptosis protein (XIAP) acts as an apoptosis blockage and directly inhibits the effector caspases (caspases 3, 6, 7, and 9) and promotes tumor formation and metastasis." (PMID 34721577, 2021). "We found a significant association of XIAP expression with younger patients’ age (≤50 years), pathological ductal type, lower tumor grade, node-positive status, and PAM50 luminal B subtype." (PMID 34199946, 2021). "Among IAPs, not only cIAP1, but also cIAP2 and X-linked inhibitor of apoptosis protein (XIAP) are overexpressed in certain tumor cells and inhibit apoptosis induced by a variety of stimuli." (PMID 32326273, 2020). "X-linked inhibitor of apoptosis (XIAP)-associated factor 1 (XAF1) is a proapoptotic tumor suppressor whose expression is commonly inactivated in a broad range of human malignancies mainly by aberrant promoter hypermethyaltion." (PMID 30042418, 2018). "Embelin is a natural product isolated from the Japanese Ardisia herb, and it exhibits anti-tumour activity through blocking the activity of the X-linked inhibitor of apoptosis protein." (PMID 28754836, 2017). "CRIB pulldown assays employing PAK-PBD in control and XIAP-depleted cells showed that the loss of XIAP also led to an increase in the GTP-bound active form of Cdc42 in normal as well as in tumor cells." (PMID 28661476, 2017). "To elucidate the biological relevance of survivin and XIAP in promoting GEP-NEC tumor growth, we performed both in vitro and in vivo loss of function experiments using a shRNA approach." (PMID 28039474, 2017). "The associations between XIAP expression and aggressive clinical behaviors and tumor progression have been found in many literatures." (PMID 29221164, 2017). "Treatment with a combination of VS-6063 and JQ1 synergistically caused an arrest of tumor cells at the G2/M phase and a decrease in the XIAP-linked cell survival." (PMID 28134933, 2017). "Upregulation of XIAP expression due to a loss of LEFTY1 causes a resistance to chemotherapy by tumor cells, resulting in tumor progression and recurrence." (PMID 28969018, 2017). "XAF1 (X-linked inhibitor of apoptosis (XIAP)-associated factor 1) is a tumor suppressor that counteracts the anti-apoptotic effects of XIAP and can sensitize cells to cell death triggering events." (PMID 28122345, 2017). "The three X variables with strongest positive correlation with tumor mass (i.e., increased in larger tumors) were cleaved caspase 3, cytochrome c, and anti-apoptotic protein X-linked inhibitor of apoptosis (XIAP)." (PMID 27077880, 2016). "XAF1 is a pro-apoptotic protein that also targets XIAP and can enhance tumor cell susceptibility to cisplatin and radiotherapy." (PMID 27613060, 2016). "Whereas HA depletion by PEGPH20 resulted in improved vasculature and increased gemcitabine delivery, blocking CTGF decreased the expression of the pro-survival protein XIAP (X-linked inhibitor of apoptosis) and induced the killing of tumour cells." (PMID 26438692, 2015). "We have reported that TGFβ/PKA/PP2A-mediated tumor suppressor signaling regulates Akt phosphorylation in association with the dissociation of survivin/XIAP complexes leading to inhibition of stress-dependent induction of cell survival." (PMID 24581231, 2014).
tumor (continued). "Paclitaxel, a known TLR-4 ligand, enhances NF-κB activity and up-regulates expression of X-linked inhibitor of apoptosis (XIAP) and pro-inflammatory cytokines known to promote tumor survival and progression in EOC." (PMID 24452475, 2014). "This modifcation occurs in the cytosol but not in the mitochondria and it is this differential phosphorylation that regulates tumor cell apoptosis, modulating the interaction of survivin with the X-linked inhibitor of apoptosis protein (XIAP)." (PMID 24429466, 2014). "Although, like survivin, its expression increased in the Pten deleted tumor tissues, XIAP appeared to be down-regulated with the loss of survivin expression." (PMID 23936028, 2013). "Western blot analysis and immunoprecipitation methods were used to determine XIAP (X-linked inhibitor of apoptosis protein) and Smac (second mitochondria-derived activator of caspase) expression and interaction in tumor cells." (PMID 23634213, 2013). "Resistance of tumor cells to NK cell-mediated death is associated with endogenous XIAP inhibiting the caspase-3 triggered by immune cell attack." (PMID 23634213, 2013). "When global translation is inhibited by the phosphorylation of eIF2α, the translation of certain mRNAs, such as GCN2, ATF4 and X-linked inhibitor of apoptosis protein (XIAP), is increased and this promotes tumor cell survival and chemoresistance." (PMID 23354132, 2013). "NFkB regulates the expression of numerous antiapoptotic proteins associated with tumor survival (bcl-xl, bcl-2, XIAP, c-FLIP, IAP-1, IAP-2, and survivin), as well as genes associated with tumor progression (cyclin D1, c-myc and COX-2)." (PMID 23145063, 2012). "Recent findings have shown in vitro, XIAP can cause resistance among tumor cells when exposed to a variety of apoptotic stimuli, including chemotherapy." (PMID 22403616, 2012). "The X-linked IAP antisense oligonucleotide (XIAP ASO-AEG35156) in paediatric tumour cell lines decreases XIAP in OS, RMS, and EW and sensitizes OS to doxorubicin, etoposide, and vincristine." (PMID 23226965, 2012). "Compounds mimicking the inhibitory effect of SMAC / DIABLO on X-linked inhibitor of apoptosis (XIAP) have been developed with the aim to achieve sensitization for apoptosis of tumor cells resistant due to deregulated XIAP expression." (PMID 21738708, 2011). "XIAP overexpression in tumour cells has been shown to cause an inhibitory effect on cell death induced by a variety of apoptotic stimuli." (PMID 20078866, 2010). "In various tumour types, elevated expression of the X-linked inhibitor of apoptosis protein (XIAP) has been observed and XIAP targeting in diverse tumour entities enhanced the susceptibility to chemotherapeutic agents." (PMID 20485285, 2010). "XIAP overexpression in tumour cells has been shown to cause an inhibitory effect on cell death besides to induce resistance to chemotherapy." (PMID 20078866, 2010). "A log-rank test showed a significant inverse association (p = 0.02) between XIAP expression and tumor aggressiveness, as indicated by disease relapse rates." (PMID 16504151, 2006). "Sept4/ARTS deficient mice have elevated XIAP levels and increased tumor incidence." (PMID 38684550, 2024). "Overall, their data showed that miR-194 acts as a tumor suppressor in colorectal carcinogenesis by targeting the PDK1/AKT2/XIAP pathway and could be an important diagnostic and prognostic biomarker for CRC43." (PMID 36854781, 2023). "In a XIAP-deficient patient, macrophages may provide an inflammatory environment, eliciting an immune response and thereby preventing tumor formation." (PMID 36270981, 2022). "The results indicate that AITC decreased the levels of myeloid cell lymphoma-1 (MCL-1), matrix metalloproteinase-9 (MMP-9), vascular endothelial growth factor (VEGF), and X-linked inhibitor of apoptosis (XIAP), and increased the expression of caspase-3, -8, and -9 in tumor sections." (PMID 36142326, 2022).
tumor (continued). "In a subsequent study, the same group identified that PN-1 may act via inhibition of X-chromsome-linked inhibitor of apoptosis (XIAP) and reported that therapeutic treatment of xenograft tumor growth in SCID mice was also synergistic with XIAP inhibitors." (PMID 33869309, 2021). "XIAP mRNA expression was heterogeneous across samples and significantly associated with younger patients’ age (≤50 years), pathological ductal type, lower tumor grade, node-positive status, HR+/HER2− status, and PAM50 luminal B subtype." (PMID 34199946, 2021). "Loss of XIAP and cIAP1 leads to stabilization of Rac1 and promotes tumor migration." (PMID 31248165, 2019). "The risk score was calculated as follows: risk score = 3.13 × (Notch4) ± 1.52 × (p-PKCα/β2) + 0.74 × (XIAP) + 0.58 × (CDK2) + 0.77 × (Akt1) + 0.74 × (TNM stage) + 1.20 × (vascular/lymphatic invasion) + 0.97 × (tumor size) + 0.61 × (age) + 0.58 × (histologic differentiation)." (PMID 31399040, 2019). "It is plausible that increased exosomal release of XIAP, Survivin and cIAP-2, and perhaps other survival and stress proteins might be linked to increased tumor aggressiveness and chemoresistance in AA-PCa patients." (PMID 28981528, 2017). "In contrast, XIAP overexpression was associated with advanced tumor stages." (PMID 28039474, 2017). "In contrast to survivin, XIAP overexpression was associated with advanced tumor stages." (PMID 28039474, 2017). "This co-association of XIAP and cleaved caspase 3 with larger tumor mass suggests that XIAP may interfere with caspase activity in larger tumors." (PMID 27077880, 2016). "In addition to the roles identified for XIAP in directly promoting tumor resistance to immune therapy, it is also likely that it is associated with the induction of a more immunosuppressive tumor microenvironment." (PMID 26821068, 2016). "Consistent with their role in the inhibition of apoptosis, XIAP and survivin are highly expressed in a diverse array of tumors and are often associated with resistance to apoptosis and low sensitivity to chemotherapy drugs in some tumor types." (PMID 25321484, 2014). "Furthermore, embelin, a derivative from Embelia ribes, is known to inhibit XIAP (X-linked inhibitor of apoptosis protein) and is able to impair tumor proliferation by interfering in IL-6/STAT3 signaling." (PMID 24901008, 2014). "The level of expression of each group (1, cIAP1-N+Survivin-N; 2, cIAP1-C+cIAP2+XIAP and 3, Survivin-C+Livin) was significantly associated with the presence of muscle-invasive disease (P1=0.001; P2=0.001; P3<0.001) and tumor grade (P1=0.003; P2=0.015; P3=0.001)." (PMID 23599779, 2013). "This may be explained by the fact that Bcl-xL and XIAP overexpression in P-glycoprotein expressing tumor cells has been associated with a much stronger resistance to treatment and a worse prognosis." (PMID 19445670, 2009). "It is reasonable to assume, therefore, that in RCCs – and probably also in AML – increased expression of antiapoptotic XIAP contributes to reduced apoptosis susceptibility of tumour cells, thereby providing an important survival advantage during tumour progression." (PMID 15328523, 2004). "Thus, CADM1 might mediate its tumor suppressor function against EBV-transformed B cells during XIAP deficiency in a cell extrinsic function that is independent of CD8+ T cells." (PMID 36270981, 2022). "In addition to assessing the effect of XIAP knockdown under normal growth conditions, we also explored whether loss of XIAP sensitizes tumor cells to either intrinsic or extrinsic inducers of cell death." (PMID 20067634, 2010). "Here we show an increased expression of XIAP in microvascular tumor thrombosis (MVTT) of HCC, which is positively correlated with the expression of extracellular signal-regulated kinases 1/2 (ERK1/2)." (PMID 42089079, 2026). "Analysis of human tumor datasets reveals a strong positive correlation between ZBTB38 and XIAP expression, with elevated ZBTB38 levels associated with high-grade malignancies." (PMID 41842907, 2026).